TNF (tumor necrosis factor)
Diseases named in the same sentence as TNF in open-access papers (continued):
Sharing a sentence is not in itself a finding about the gene and the disease.
cancer (continued). "The dominate pathways including Wnt signaling pathway, TNF signaling pathway, VEGF signaling pathway, and NF-κB signaling pathway were strongly inhibited by SA, which are involved in regulating cancer metastasis." (PMID 33708105, 2020). "The cancer tissue concentrations of TNF-α and MDA were considerably greater in treated cancers than in controls, and these results were related to the histological modifications." (PMID 32455998, 2020). "Given that IAP proteins block apoptosis caused by TNF, and considering that IAP antagonists have profound effects in potentiating solTNF-induced apoptosis, we hypothesized a combination treatment with IAP antagonists Smac mimetics (S) would further sensitize cancer cells to MTA-induced apoptosis." (PMID 31645676, 2020). "In this study, we focused on building GRCs using the single cell RNA sequencing (scRNA-seq) data collected from Cook and Vanderhyden (2019) for four cancer cell lines (A549, DU145, MCF7, and OVCA420) treated with EGF, TGFB1, and TNF." (PMID 32391378, 2020). "GMI inhibits tumor necrosis factor alpha (TNFα)-mediated matrix metallopeptidase 9 (MMP-9) expression and migration in A549 cancer cells." (PMID 33382817, 2020). "Various signaling pathways are involved in inducing EMT in cancer including Notch, Wnt, transforming growth factor‐beta, HIF‐1α, and TNF‐α and extracellular matrix stiffness." (PMID 31725949, 2020). "According to the results of KEGG, the common target genes of PLC and CCMMs were mainly enriched in cancer-related signaling pathways, such as pathways in cancer, PI3K-Akt pathway, TNF pathway, and MAPK pathway." (PMID 32382293, 2020). "ESM1 is known to be upregulated by inflammatory cytokines (IL-1β, TNF-α, and IFN-γ) and proangiogenic factors (VEGF-A and VEGF-C) and PI3K dependent pathway in cancer cell or endothelial cell." (PMID 32466580, 2020). "KEGG pathway analysis indicated that upregulated genes in P2 were enriched in TNF, JAK-STAT, IL-17, B cell receptor, Chemokine, NF-kappa B, T cell receptor signaling pathway and PD-L1expression and PD-1 checkpoint pathway in cancer." (PMID 33378744, 2020). "Based on their application as cancer treatments, NK cells are known to exert direct cytotoxic effects on virally infected cells and produce IFN-ƴ and TNFα to boost the host immune response." (PMID 33059711, 2020). "These include TNFα, IFNγ, and TLR4, which are notorious mediators of muscle atrophy under conditions of experimental cancer cachexia." (PMID 33330108, 2020). "Because of its role in signalling by both TNF and ligands of the EGF receptor, it has been the focus of major pharmaceutical efforts, with a view to treating inflammatory diseases and cancer." (PMID 32715522, 2020). "Interferon gamma, IL-6, TNFα, and TRAIL are all secreted signaling molecules that have prominent roles in the regulation of cell death in various cell types, including cancer cells in addition to their immune regulatory functions." (PMID 33375357, 2020). "Second, we used TNF-α, one of the NF-κB stimulants to clearly show the effects of AIM on NF-κB activity and NF-κB-regulated proteins involved in cancer metastasis because base-line NF-κB activity of MCF-7 cell was low." (PMID 32455624, 2020). "Since TNF-α triggers MACC1 expression, we were interested in identifying the responsible receptor mediating this effect in cancer cells." (PMID 32670264, 2020). "These viruses contain the ARE of the TNF-α and c-fos genes in the 3′-UTR of the E1A gene, which allows them to replicate specifically in ARE-mRNA-stabilized cancer cells." (PMID 32403262, 2020). "Future studies are needed to determine if the TNF-Fc fusion proteins can improve protection in CDN-adjuvanted vaccines for infectious diseases and cancers in the elderly." (PMID 32849581, 2020). "They found that swimming increases INF-γ and TNF-α cytokines; however, it decreases anti-inflammatory cytokines such as TGF-β and IL-10 in mice models with cancer." (PMID 32405368, 2020).
cancer (continued). "KEGG analysis showed that DEGs were mainly enriched in four cancer‐related signaling pathways including MAPK signaling pathway, ERBB signaling pathway, IL‐17 signaling pathway and TNF signaling pathway." (PMID 32441484, 2020). "Chronic inflammation in cancer is induced in the TME through the expression of pro-inflammatory cytokines, such as PGE2, GM-CSF, G-CSF, M-CSF, SCF, S100 proteins, VEGF, TGFβ, and TNFα." (PMID 32121014, 2020). "Inflammation plays a supportive role in facilitating this process, TNF in the microenvironment stimulates the release of pro-angiogenic factors IL-6, IL-8, TGF-β, and vascular endothelial growth factor (VEGF) by cancer cells via the induction of NF-κB." (PMID 33076397, 2020). "Other genes overexpressed in Cluster 1 were chemokine and cytokine related genes (CCL15, CCL18, TNF, IL11RA, XCR1), the immune checkpoint protein PD-1 (PDCD1), and cancer-related genes (SSX1 and MAGEA4)." (PMID 33298930, 2020). "Tumor-necrosis factor-α (TNF-α), vascular endothelial growth factor (VEGF), and TGF-β1 secreted from TAM can promote the cancer metastasis." (PMID 32987868, 2020). "The top pathways (count number ≥ 15) included cancer, PI3K-AKT, MAPK, TNF, focal adhesion, prolactin, HIF-1, thyroid hormone, FoxO, Rap1 and Ras signaling pathways." (PMID 32450873, 2020). "IL-6 activates the JAK/STAT3 pathway and promotes angiogenesis, invasion, metastasis, and TNF-α activate EMT and promote cancer progression." (PMID 32796516, 2020). "TNF-α, IL-6 and COX-2 are considered to be important cytokines linking inflammation and cancer, which are also recognized to play an indispensable role in the development and progression of CAC." (PMID 33603669, 2020). "For the purpose of correlation analysis we have retrieved data on systemic concentrations of IL-1β, IL-4, IL-6, IL-8, IL-12p70, FGF2, G-CSF, GM-CSF, MCP-1, MIP-1α, PDGF-BB, TNFα, and VEGF-A, available for 43 of our cancer patients." (PMID 33020452, 2020). "Correlation analyses between YIF1B and checkpoint gene expression found a high correlation (P<0.05) with tumor necrosis factor (TNF)-related immune genes (TNFRSF4, 8, 14, 18) and CD276 (B7H3) in various cancer types." (PMID 32648580, 2020). "Recent findings demonstrate that one NK cell population possesses potent cytolytic activity against targeted cancer cells, while others uniquely secrete various inflammatory cytokines (IFN-γ, TNF-α, and GM-CSF) and chemokines (CCL3 and CCL5)." (PMID 32231116, 2020). "In this study, we showed that TNFα+CHX and navitoclax-induced cancer cell pyroptosis through a BAK/BAX-caspase-3-GSDME signaling pathway." (PMID 32332857, 2020). "Therefore, we suppose that a high level of TRAIL or TNF in cancer might make SMs more efficient." (PMID 32325691, 2020). "Addition of LCL161 to paclitaxel therapy increased TNF expression, degradation of cIAP1/2 and activation of caspase-8 dependent apoptotic signaling, sensitizing NSCLC cancer cells to treatment in vitro." (PMID 32053868, 2020). "TNF-α also activates expression of TIM-3, which enables Gal-3, expressed on cancer cells, to block T cells by combing with TIM-3 on T cells membrane." (PMID 32310956, 2020). "Tumor necrosis factor-α (TNF-α) plays a significant role in inflammation and cancer-related apoptosis." (PMID 32455774, 2020). "Tumor necrosis factor (TNF- α-308 G/A and TNF-β +252 A/G ) are inflammatory cytokine that control the progression of several types of cancer." (PMID 32102503, 2020). "TRAIL is a member of the tumor necrosis factor (TNF) superfamily which is able to form homotrimer with death receptors (DRs) on the cell membrane; when it does, it triggers apoptosis pathway in cancer cells and has a negligible effect on normal cells." (PMID 33381459, 2020).
cancer (continued). "Based on the outcomes of pathway enrichment, SM and RP active ingredients can simultaneously target cancer pathways, neuroactive ligand-receptor interactions, and PI3K-Akt and TNF signaling pathways, leading to the synergistic effect of SM and RP." (PMID 33082828, 2020). "Here, we investigated the effects of TNF-α pretreated with AIM on NF-κB-regulated proteins in MCF-7 cells, focusing on cancer metastasis involved in cancer invasion, adhesion, and angiogenesis." (PMID 32455624, 2020). "The use of TNF-α appears to be artificial, but in the process of cancer metastasis, TNF-α or other cytokines from cancer and surrounding inflammatory cells play an important role in metastasis." (PMID 32455624, 2020). "γδ T cell protection against cancer is mainly reported to be through the production of proinflammatory cytokines such as IFN-γ, TNF-α, and IL-17 as well as through their cytotoxic ability." (PMID 32391048, 2020). "The Matrigel test revealed that TNF-α significantly increased cancer cell invasion, and that AIM also significantly reduced cancer cell invasion augmented by TNF-α." (PMID 32455624, 2020). "M1 macrophages produce type 1 helper T (Th1) cytokines (IL-6, IL-8, IL-12, and tumor necrosis factor (TNF)-α), leading to primarily anti-cancer responses." (PMID 32408477, 2020). "Despite previous reports mainly focused on the anti-cancer activities of AIM, here, we mainly focused on the inhibition of the TNF-α induced effect by AIM." (PMID 32455624, 2020). "For example, MMP2, MMP3, and MMP9 are direct or indirect target genes of FoxO3a in endothelial as well as cancer cells, and FoxO4 upregulated MMP9 expression in smooth muscle cells stimulated by tumor necrosis factor‐α (TNF‐α) by an indirect mechanism." (PMID 32790044, 2020). "Cancer-related proinflammatory cytokines, such as interleukin-6 (IL-6) and interleukin-1 (IL-1), as well as tumor necrosis factor-α (TNF-α) inhibit albumin production, leading to cancer cachexia." (PMID 33176752, 2020). "Tumor necrosis factor (TNF)-related apoptosis-inducing ligand (TRAIL) induces cancer cell-specific apoptosis and has garnered intense interest as a promising agent for cancer treatment." (PMID 33396409, 2020). "The cytokines extruded are the tumor necrosis factor (TNF)-α and INF-γ, which both play key roles in antiviral effects and immunosurveillance of cancer." (PMID 33194688, 2020). "A solution towards a resistant form of cancer was proposed as inhalable self-assembled nanoparticles comprised of human serum albumin (HSA), tumor necrosis factor (TNF)-related apoptosis-inducing ligand (TRAIL) and Dox." (PMID 31973051, 2020). "Our results, along with the findings of other authors, indicate the ability of the CV extract to induce the production of many cytokines, including IL-1β, IL-2, IL-6, IL-10, TNF-α, and IFN-γ, by immune cells and cancer cells." (PMID 33260615, 2020). "RhoC is a well-known oncogene that enhances the migration and invasive ability of cancer cells, and TNF-α increases the blood–brain barrier (BBB) permeability and penetration of cancer cells into the brain." (PMID 31900168, 2020). "The inflammatory cytokines interleukin-1 beta (IL-1β) and tumor necrosis factor-alpha (TNF-α) were reported to induce Nurr1 expression, which, in the presence of TGF-β, potentiates SMAD activation of cancer development." (PMID 33086676, 2020). "The cytokines IL-6 and TNF-α and transcription factors, STAT3 and NFKB contribute to both inflammation and cancer development." (PMID 32731413, 2020). "ROS can activate nuclear factor-κB (NF-κB) to promote the expression of proinflammatory cytokines, such as tumor necrosis factor (TNF)-α, interleukin-1β, cancer cell growth, cell invasion, and the expression of antiapoptotic protein Bcl-2." (PMID 32498451, 2020). "TNF-α is a cytokine secreted as part of the inflammatory process that accompanies RTH and the development of cancer itself." (PMID 31076897, 2020).
cancer (continued). "Based on KEGG pathway analysis, we also evaluated several cancer-related pathways in AITL, including PI3K-Akt signaling pathway, NF-κB signaling pathway, cell cycle, apoptosis, and TNF signaling pathway." (PMID 31892973, 2020). "The queens with TN normal-like carcinomas also showed a strong positive correlation between serum PD-1 levels and serum PD-L1 (r = 0.857), CTLA-4 (r = 0.927) and TNF-α (r = 0.893) levels." (PMID 32481540, 2020). "Other inflammatory mediators involved in CRC, such as TNFα and NOS2, were also inhibited by Emodin during the progression from inflammation to carcinoma, through transcriptional regulation." (PMID 33489875, 2020). "The combined therapy of cucurbitacin I and recombinant IL-15 is also reported to exhibit immunologic anti-cancer activities in lymphoma with increased CD4+ and CD8+ T cell differentiation, and promote DC function through TNF-α up-regulation." (PMID 31719837, 2019). "The present study also supports the utility of saliva in biomarker estimation and in evaluating TNF- α as a prognostic marker, also as an indicator for the neoplastic transformation from OPMD to cancer and in mass screening programmes." (PMID 31350970, 2019). "Results obtained in these studies indicated that 33 synergizes with TNF‐α (and anticancer drugs) as well as augments anticancer effect of TNF‐α, one of the essential cytokines involved in regulation of cancer." (PMID 30548868, 2019). "IL-1β, IL-6, TNF-α, IL-4, IL-10, and TGF-β are among the most well studied cytokines known to effect cancer initiation/progression and sleep." (PMID 31174326, 2019). "The other clusters in this network are related to signaling pathways of NF-kappa B, TNF, NOD-like receptor, T cell receptor, mTOR, Chemokine, MAPK, Toll-like receptor and pathways in cancer." (PMID 31776371, 2019). "However, several studies suggested no increased risk of overall cancers with TNF inhibitors." (PMID 31626313, 2019). "Ilexgenin A, rosmarinic acid, and lupeol target proinflammatory cytokines, such as TNF-α, to inhibit VEGF and ultimately provide relief against the pain in cancer immunotherapy." (PMID 30871059, 2019). "The concept of non-death domain TNF super family receptors (TNFSFR) involved in cell death has been previously reported in cancer cell lines for FN14, CD40, TNFR2, and CD30, acting through a TNF/TNFR1 axis." (PMID 31541082, 2019). "Considering the relation of TNF-α and the progression of different types of cancer, based on clinical data and the importance of Pgp in chemotherapy failure, we suggest that rTNF-α could support the MP release of cancer cells and spread Pgp to maintain an MDR phenotype." (PMID 31137684, 2019). "Other evidence has suggested that complement proteins induce the production of TNF-α and TGF-β in pathological processes such as cancer." (PMID 31485295, 2019). "Here we comparatively studied the expression of various TNF/TNFR family members on platelets and lymphocytes of cancer patients and healthy controls." (PMID 30813611, 2019). "For example, in cancer cells, SAHA can activate apoptosis, the accumulation of reactive oxygen species (ROS) and the activation of tumor necrosis factor α (TNFα) family members." (PMID 30745455, 2019). "The role of ADAM17 in cancer has been widely reported, especially following the discovery of a direct effect of ADAM17 on the release of TNFα." (PMID 31565100, 2019). "TNF-α derived from M2 TAMs promotes EMT and cancer stemness through the Wnt/β-catenin pathway in SMMC-7721 cells of HCC." (PMID 31572568, 2019). "CCL8 treatment of both cancer cell lines significantly upregulated the expression of CSF1 mRNA and protein (Log2FC > 1, p < 0.05), as well as TNF-α and IL-1β." (PMID 30930117, 2019).
cancer (continued). "TNFα, produced by macrophages, may act as a metabolic hormone blocking insulin signaling or production, as TLRs do, but also as a regulator of the immune response, therefore being a representative molecule linking inflammation, metabolism, immune response, and cancer." (PMID 30764482, 2019). "Breast cancer TAMs express CCL8, which is chemotactic for monocytes and drives a positive regulatory loop between cancer cells and TAMs through CSF1 and TNF-α, which upregulates SIGLEC1." (PMID 30930117, 2019). "Various factors, including PIF (tumor-derived factor), myostatin (skeletal muscle-derived factor), and cytokines, such as TNF-α and IL-6, can facilitate skeletal muscle depletion by inhibiting the PI3K/Akt signaling in cancer cachexia." (PMID 30754663, 2019). "Many of the key drivers of neoplastic progression, such as neutrophils, MDSCs, TAMs, and Tregs cells, work by secretion of pro-inflammatory cytokines, including IL-1, IL-6, TNF, and TGF-β, providing a basis for a link between inflammation and cancer." (PMID 31769418, 2019). "We therefore examined the expression levels of tumor necrosis factor-α (TNF-α), interleukin-1 (IL-1), and IL-6, 3 key cytokines that contribute to cancer-induced bone pain." (PMID 31488714, 2019). "Nonetheless, TICIMEL will allow for the assessment of the safety of combining anti-TNF and ICB in cancer patients within a clinical trial specifically designed for this purpose." (PMID 31727152, 2019). "Overall, these findings suggest that TNF-β, like TNF-α, promotes CRC cell activation, progression, and metastasis, increasing CSCs and thereby enhancing the malignancy of the cancer cells." (PMID 30917533, 2019). "mPD-L1/mPD-1 can be induced by multiple inflammatory cytokines in cancer, including IFN-γ, IL-6, IL-10, IL-17 and TNF-α." (PMID 30506460, 2019). "Secondly, together with TNFα, IL6 is a major inflammation inducer which activates STAT3, resulting in cancer progression." (PMID 31398937, 2019). "Gene-set enrichment analysis of hallmarks of cancer pathways has shown that several important pathways are upregulated in response to SK1/SK2 KD, most notably KRAS, IL2/STAT5, EMT and TNF/NFκB (SK1 KD) and EMT, G2/M and E2F (SK2 KD)." (PMID 30971929, 2019). "The tumor necrosis factor (TNF) superfamily member tumor necrosis factor-related apoptosis-inducing ligand (TRAIL) is a potent inducer of apoptosis that may have significant broad ranging applications in cancer therapy due to its selectivity toward cancer cells." (PMID 31248045, 2019). "SMO is induced by tumor necrosis factor (TNF), resulting in the production of H2O2 which adds to inflammation, mutagenesis, and subsequently cancer development." (PMID 31354753, 2019). "Since all patients included in this cohort received anti-TNF following the emergence of irAEs, the impact Infliximab has on ICB response in cancer patients cannot be extrapolated." (PMID 31727152, 2019). "Several studies have shown that higher DII score is associated with elevated levels of inflammatory mediators, which include TNF-α, IL-6 and hs-CRP, indicating strong link between DII and cancer." (PMID 31652856, 2019). "One of the functions of adamalysines is the activation of growth factors involved in cancer, including IGF and TNFα." (PMID 31565100, 2019). "Potent and selective anticancer activity has been observed in mouse models of cancer (particularly for fusion proteins based on IL2, IL12 and TNF payloads)." (PMID 31803362, 2019). "Cytokines like IL-2, IFN-γ,TNF-α and thymosin are FDA approved immunostimulator for cancer treatment (renal cell carcinoma)." (PMID 31661003, 2019). "In contrast, genes that replicate later and are downregulated are enriched in terms related to cancer such as EMT, TNFα signalling, KRAS signalling, cell movement and cell proliferation." (PMID 30679435, 2019).